GDNF (glial cell derived neurotrophic factor)
Diseases named in the same sentence as GDNF in open-access papers (continued):
Sharing a sentence is not in itself a finding about the gene and the disease.
infectious disease (1 paper, 2011). A disorder directly resulting from the presence and activity of a microbial, viral, or parasitic agent in humans. "Although the GDNF was upregulated in the inflamed gut tissues of CD (335 ± 86 pg/ml), it was statistically less than in UC patients or in infectious disease (p < 0.05)." (PMID 21235736, 2011).
intestinal diseases (1 paper, 2023). "Reduced levels of GDNF lead to morphological and functional abnormalities of the intestinal barrier function, both in patients with intestinal diseases and in preclinical models." (PMID 36902407, 2023).
GDNF also shares sentences with these, for which no sentence is quoted: Parkinson's (29 papers); attention deficit-hyperactivity disorder (4); autism (3); amyloid (2); central nervous system disorder (2); cerebrovascular disease (2); CNS tumors (2); digestive system diseases (2); endometriosis (2); fibrosis (2); movement disorder (2); osteoarthritis (2); peripheral neuropathies (2); somatotroph adenomas (2); testicular tumors (2); Tourette syndrome (2); acquired immunodeficiency syndrome-associated dementia (1); alcohol addiction (1); alopecia (1); bacterial infection (1); brain cancer (1); cerebral infarction (1); channelopathy (1); cholangiocarcinoma (1); chondrodysplasia (1); chronic headache (1); chronic hepatitis B (1); chronic kidney disease (1); chronic obstructive pulmonary disease (1); cognitive disorder (1).
A further 59 diseases each share a sentence with GDNF in 1 paper.